JAK2 (Janus kinase 2)
Diseases named in the same sentence as JAK2 in open-access papers (continued):
Sharing a sentence is not in itself a finding about the gene and the disease.
breast cancer (continued). "Another interesting study found that VEGFR-2 recruits JAK2/STAT3 to activate embryonic stem cell transcription factors MYC and SOX2 in breast cancer CSCs." (PMID 26500608, 2015). "Activation of the PI3K/AKT pathway, IL-6/JAK2/STAT3 pathway, and stem cell-like characteristics contribute to the poor outcomes of metastatic breast cancers." (PMID 26515594, 2015). "While the JAK2/STAT5 cascade is the major physiological pathway for PRL actions in mammary function, SFKs mediate many PRL signals in breast cancer." (PMID 25607819, 2015). "Our studies have shown that prolactin produced in breast cancer cells through intracrine activation of PRLR and via at least two signal transduction pathways, JAK2/STAT5 and JAK2/PI3K/MEK/ERK, up-regulates the human prolactin receptor." (PMID 25193864, 2014). "Envisioning an application in preventing breast cancer in women having a late age pregnancy who may have already accumulated precancerous cells, we prophylactically treated fully involuted, early lesion-bearing mice with several small molecule inhibitors targeting Jak2 or STAT5 activity." (PMID 24381245, 2013). "We also report that a highly specific AHR agonist significantly (P < 0.05) inhibits the expression of E2F1, CCND1 (known as Cyclin D1), MYB, SRC, JAK2, and JUND in breast cancer cells." (PMID 24171117, 2013). "In breast cancer cells, PRL activates Jak2, stimulates phosphorylation of Stat1, Stat3 and Stat5 and induces cell proliferation." (PMID 23317095, 2013). "Similarly, CCL18, a TAM-secreted chemokine, activates JAK2/STAT3 signaling in ESCA, correlating with poor prognosis, as seen in ovarian and breast cancers." (PMID 40134607, 2025). "Therefore, JAK2 inhibitors have the potential to become a new therapeutic method for triple-negative and HER-2 positive breast cancers." (PMID 38872110, 2024). "Subsequently, we performed qRT–PCR for verification, and the results showed that after adding GluOC into MDA-MB-231 breast cancer cells, the levels of ROCK1, JAK2, PIK3CA, Bcl-2, CREB were significantly increased, while the expression levels of Bax were significantly decreased." (PMID 39054484, 2024). "Moreover, we have unpublished results demonstrating that Mirlet7d reduced cancer hallmarks in breast cancer cells by degradation of MAFG-AS1 and suppression of the JAK2/STAT2 signaling pathway." (PMID 38473229, 2024). "Notably, LCK showed significantly higher expression in TNBC compared to normal tissues and other breast cancer subtypes, whereas MAPK1 and JAK2 exhibited much lower expression in TNBC compared to normal tissues and other breast cancer subtypes." (PMID 39867914, 2024). "Induction of the TEM from melanoma cells, transfer of miRNAs supporting 1-integrin-NF-kB signaling from metastatic liver cancer cells, improvement of breast cancer cell motility and ECM remodeling pathways, and activation of SOCS1/JAK2/STAT3 signaling from melanoma cells." (PMID 39187523, 2024). "Of interest, they found that inhibition of JAK2, STATA3, or lncRNA-BM may prevent breast cancer brain metastases." (PMID 37077610, 2023). "Moreover, downregulation of prolactin-mediated JAK2/STAT5A signaling by Mucuna pruriens, an ancient Indian medicinal plant enhanced cisplatin efficacy in the treatment of breast cancer cells." (PMID 38124049, 2023). "In addition, JAK2 and STAT5A overexpression cooperatively reverses EMT and promotes differentiation in human breast cancer cells, which explains the suppression of invasion of prolactin-activated STAT5A in mammary cancer cells." (PMID 38124049, 2023). "Mechanically, BC069792 acts as a molecular sponge to adsorb hsa-miR-658 and hsa-miR-4739, to up-regulate the protein expression of Potassium Voltage-Gated Channel Q4 (KCNQ4), inhibits the activities of JAK2 and p-AKT, and plays a role in inhibiting breast cancer growth." (PMID 36859185, 2023).
breast cancer (continued). "In addition to that, apigenin was demonstrated to suppress JAK2 and STA3 phosphorylation in breast cancer and hepatocellular carcinoma cells." (PMID 36422572, 2022). "A large number of studies have shown that IL-6/JAK2/STAT3 signaling pathway is abnormally highly activated in a variety of cancers, such as gastric cancer (GC), breast cancer (BC), liver cancer, colorectal cancer (CRC), colon cancer, ovarian cancer (OC), lung cancer, pancreatic cancer (PC)." (PMID 36591515, 2022). "The pre-clinical assessment of JAK2 inhibition in combination with SMO-GLI1/tGLI1 inhibitors demonstrated the synergistic inhibition of primary tumor growth and metastasis, prolonging survival in rodent breast cancer models." (PMID 35053592, 2022). "We also aimed to explore the involvement of JAK2/STAT3 signaling pathway and if treatment with CPT and naringenin could eventually lead to suppression of tumor growth in a mouse model of breast cancer." (PMID 35606804, 2022). "The JAK2 pathway plays a critical role in PRL-induced proliferation of normal mammary epithelial cells, as well as in human breast cancer cells, and we have previously shown that PRL induces proliferation of different breast cancer cells." (PMID 35089929, 2022). "JAK2 knockdown (KD) in human acute myelogenous leukemia (AML) cell line, STAT1 KD in human T cell acute lymphocytic leukemia cells, Stat3 KD in mouse mammary tumor, and STAT3 KD in human urothelial cancer cells resulted in zero to two OCRG upregulation and one to five OCRG downregulations." (PMID 34368262, 2021). "Given the observed co-activation of JAK2 and TrkA in triple-negative and HER2-enriched breast cancers, we speculate that co-targeting of JAK2 and TrkA would be a promising new therapeutic modality against breast cancer." (PMID 34066153, 2021). "In addition, correlation analysis from bc-GenExMiner v4.5 revealed that the expression of HDAC2, as well as JAK1, JAK2, and STAT1, was significantly correlated with that of PD-L1 in breast cancer." (PMID 34365463, 2021). "It inhibits the cell proliferation and metastasis by targeting Janus kinase 2 (JAK2)/signal transducer and activator of transcription 3 (STAT3)-mediated EMT process in GC and by targeting p21-activated protein kinase 2 (PAK2) in breast cancer." (PMID 33028884, 2020). "To further elucidate the pathway dependency in a panel of breast cancer cell lines, we depleted both JAK1 and JAK2 kinases (upstream regulators of STAT proteins) and found that TNBC cell lines are more likely to be dependent on JAK2 than JAK1 for survival." (PMID 30777101, 2019). "We also report that the levels of STAT-3 and JAK-2 were found to be constitutively active in the BT549 breast cancer cell line and treatment with HGF and/or BFE had no bearing on the phosphorylational status." (PMID 30314527, 2018). "Moreover, it has been reported that OPN activates JAK2/STAT3 signaling and upregulates Bcl-2 and cyclinD1 in human breast cancer cells." (PMID 28505114, 2017). "Consistent with our findings, expression of dominant-negative Stat3 or treatment with a JAK2/Stat3 inhibitor in breast cancer cell lines inhibited cell growth." (PMID 27589562, 2016). "CD44 also can interact with JAK2 and STAT3 to activate STAT3 in breast cancer." (PMID 27521216, 2016). "In addition, in breast cancer, IL-8 (interleukin-8) secretion following JAK2/STAT5 (Janus kinase 2/signal transducer and activator of transcription 5) activation has also been shown to counteract the anticancer efficacy of PI3K inhibitors." (PMID 26404259, 2015). "Although JAK2/STAT5 represents the principal physiological pathway of PRLR’s action, the signaling to SFKs by this receptor could also play a role in breast cancer progression." (PMID 26733941, 2015). "Moreover, it has been demonstrated that JAK2/STAT5 signaling and AKT1 play essential roles during mammary tumor initiation in various murine cancer models." (PMID 24628780, 2014).
breast cancer (continued). "Here, we report that AMD3465 triggers a reduction in breast cancer cell invasiveness in vitro, and promotes marked changes in oncogenic signaling proteins including a reduction in STAT3, JAK2, AKT, and CXCR4 phosphorylation and the reduced expression of GSK3 and cMYC." (PMID 23484027, 2013). "No further data are published on Δ1–9 in breast cancer, however it has been shown to induce apoptosis in prostate cancer cell lines by antagonising autocrine prolactin-mediated janus kinase 2 (JAK2)/STAT5A/B signalling." (PMID 18681966, 2008). "In the context of the most aggressive breast cancer, it is important that leptin could crosstalk with HER2 either through ObR, HER1, and JAK2." (PMID 18945363, 2008). "Failure of rEPO to induce the tyrosine phosphorylation of JAK2 or STAT5 was also observed in human breast cancer cell lines MCF-7 and MDA-MB-231 (data not shown)." (PMID 17579721, 2007). "Compared with those in the Y-27632 inhibitor group, the P-JAK2 and P-PIK3CA protein levels were significantly increased after the addition of GluOC, and the results showed that ROCK1 regulated JAK2 and PIK3CA, thereby affecting the proliferation and apoptosis of MDA-MB-231 breast cancer cells." (PMID 39054484, 2024). "Specifically, lapatinib (0.8 μM), a HER2 inhibitor, was used for breast cancer (MCF7); gefitinib (15 μM), an EGFR inhibitor, for lung cancer (H358); dasatinib (70 nM), an Src inhibitor, for prostate cancer (LNCaP); and finally, AZD1480 (6 μM), a JAK2 inhibitor, for hepatocellular carcinoma." (PMID 38892372, 2024). "In breast cancer, the non-receptor tyrosine kinase JAK2 is typically overexpressed and activated." (PMID 37711177, 2023). "JAK2 has been previously utilized as an immunotherapeutic target for breast cancer; however, there is little evidence of its successful targeting in AML so far, although it could provide a novel therapeutic approach." (PMID 37298623, 2023). "Currently, combinations of FDA-approved JAK2 inhibitors, including ruxolitinib (Rux) and pacritinib (Pac), and SMO inhibitors including vismodegib (Vis) and sonidegib (Son) exerted synergistic cell kill in a HER2-positive breast cancer cell lines with acquired trastuzumab resistance." (PMID 37174034, 2023). "Moreover, circ-NOL10 sponges miR-767-5p in breast cancer (BC) to promote the expression of suppressors of cytokine signaling 2 (SOCS2) and attenuate janus kinase 2/signal transducer and activator of transcription 5 (JAK2/STAT5) signaling, therefore preventing cancer progression." (PMID 37587156, 2023). "In breast cancer (BC), exosomal SNHG1 promotes the proliferation, migration, and angiogenesis of HUVECs via the miR-216b-5p/JAK2 axis." (PMID 35326397, 2022). "Moreover, the observed co-activation of JAK2-STAT3 and SHH signaling pathways suggests that combination of JAK2 and SMO inhibitors may synergize against TNBC and HER2-enriched breast cancers." (PMID 32957513, 2020). "Alternatively, based on the reported role of SOCS proteins in inhibition of mutant Jak2 and suppression of cytokine-independent signaling, downregulation of SOCS genes in breast cancer tissues may trigger some cytokine-independent pathways resulting in cell transformation." (PMID 30453988, 2018). "This is also in line with the finding that the activation state of the tyrosine kinases JAK1, JAK2, and c-Src, which are considered to be responsible for phosphorylation of STAT3 Tyr705, was not significantly inhibited by the presence of 10 or 20 mM STATTIC in breast cancer cells." (PMID 30283459, 2018). "The activity of Janus kinase 2 (JAK2) is inhibited by ninein, constitutive activation of JAK2/STAT5 promotes resistance to apoptosis and contributes to tumorigenesis of breast cancer, these suggest ninein may inhibit the development and progression of breast cancer." (PMID 26883017, 2016).
breast cancer (continued). "Moreover, the IL-6/STAT3/JAK2 pathway is involved in the maintenance of stem cell–like cancer cells because CD44+CD24+ and CD44+CD24− breast cancer cells have high phospho-STAT3 via their expression of genes such as IL6, PTGIS, and HAS1, which activate an autocrine loop." (PMID 26515594, 2015). "In this study, we have shown that in breast cancer cells, regulation of PRLR gene expression at the transcriptional level by its own ligand, independent of E2, can take place with the essential participation of the JAK2/STAT5 and mitogen-activated protein kinase (MAPK) signaling pathways." (PMID 25193864, 2014). "However, in mammary carcinoma cells, we did not observe any significant changes in the tyrosine phosphorylation of JAK2 in cells expressing EPOR-R129C." (PMID 17579721, 2007). "Moreover, rEPO treatment failed to induce the tyrosine phosphorylation of JAK2 or STAT5 in mammary carcinoma cells, even following longer time-course stimulation of the cells with rEPO (data not shown)." (PMID 17579721, 2007). "In contrast to the well-established signaling pathway activation mediated by EPO-EPOR in hematopoietic cells, EPO treatment of mammary carcinoma cells did not induce the phosphorylation of the JAK2/STAT5 axis- a critical pathway for physiologic EPOR function in hematopoietic cells." (PMID 17579721, 2007). "Another study found that the overexpression of MUC16 induces breast cancer cell proliferation via its interaction with the non-receptor tyrosine kinase JAK2, and this interaction mediates phosphorylation of transcription factor STAT3, which may transactivate c-Jun for Cyclin D1 expression." (PMID 39149564, 2024). "However, some studies have also shown that STAT1 can induce platinum resistance in breast cancer, which may be independent of the activation of JAK2/3." (PMID 36911202, 2023). "The EGFR inhibitors, which are principally used in non-small cell lung cancers or breast cancers, may act on SARS-CoV-2 virus replication, whereas JAK2 inhibitors could act on SARS-CoV-2 cytokine storm because IL-6 and GM-CSF, which are stimulated in this infection, depend on JAK2 signaling." (PMID 34864885, 2022). "Our results reveal that JAK2/PAK1 dysregulation inhibits the Stat3 signaling pathway and CSC formation, the PAK1/Stat3 complex regulates IL-6 gene expression, PAK1/Stat3 signaling regulates CSC formation, and PAK1 may be an important target for treating breast cancer." (PMID 31658701, 2019). "JAK2 and STAT3 mutations both showed a trend toward being more frequent in distant metastasis samples, which may explain why these were detected as significant in our study but not in previous studies of primary breast cancer." (PMID 28810143, 2017). "To test whether GH signaling in human T47D breast cancer cells, which express low levels of GHR and high levels of PrlR, is affected by extracellular acidosis, we assessed GH induction of phosphorylation of Jak2, Jak1 and Stat5 across a range of zinc ion concentrations at pHe 7.4 and 6.8." (PMID 24004716, 2013). "LEP signaling cascade promotes breast cancer cell proliferation, migration, and invasion through the activation of MAPK, PI3K/AKT, JAK2/STAT pathways, and EMT, irrespective of BC subtypes, primarily in post-menopausal women." (PMID 36291602, 2022). "Janus kinase 2 (JAK2) is a non-receptor tyrosine kinase that is frequently amplified or aberrantly active in triple-negative and HER2-enriched breast cancers." (PMID 34066153, 2021). "STAT3 is an oncogenic transcription factor that is downstream of Janus-activated kinase 2 (JAK2), a non-receptor tyrosine kinase commonly amplified and hyperactive in TNBC and HER2-enriched breast cancers." (PMID 32957513, 2020). "In contrast, Hodgkin's lymphoma HLDM-2 cells, breast cancer MDA-MB-468 cells and prostate cancer DU145 cells exhibited high levels of phospho-JAK1 and -JAK2 but not phospho-JAK3." (PMID 20149240, 2010).
breast cancer (continued). "This notion was substantiated by experiments in which we tested the effect of two JAK2 inhibitors, [(E)-3-(6-bromopyridin-2-yl)-2-cyano-N-((S)-1-phenylethyl) acrylamide, WP1066] and FDA-approved Tofacitinib in the presence and absence of doxorubicin on the resistant breast cancer cells." (PMID 29383118, 2017).
essential thrombocythemia (322 papers, 2009 to 2026). A chronic myeloproliferative neoplasm that involves primarily the megakaryocytic lineage. "Myeloproliferative syndromes, including essential thrombocythemia, can result from mutations in the JAK2, CALR, and MPL genes, each acting as drivers of the fusion protein BCR-ABL1 to increase cell (platelet as well as leukocyte) production." (PMID 39954672, 2025). "Here, we report a case of an adult-onset DM patient with anti-TIF1γ antibody, who also suffered from essential thrombocytosis related to the JAK2 V617F mutation." (PMID 40574830, 2025). "Summary of studies reported adrenal hemorrhage (AH)/infarction (AI) caused by JAK2 V617F-positive essential thrombocythemia." (PMID 40809165, 2025). "Laboratory evaluation revealed an elevated platelet count, and genetic testing confirmed the presence of the JAK2 V617F mutation, suggestive of essential thrombocythemia." (PMID 39877786, 2024). "JAK2 V617F, the most prevalent mutation in cMPNs, is detected in over 95% of polycythemia vera (PV) cases and approximately 50–60% of essential thrombocythemia (ET) and primary myelofibrosis (PMF) cases." (PMID 39685591, 2024). "The JAK2 V617F mutation is found in approximately 50-60% of patients with essential thrombocythemia." (PMID 39429993, 2024). "A bone biopsy, as well as flow cytometry and genetic tests, was carried out to confirm the diagnosis of essential thrombocythemia (ET) with the V617F mutation of the Janus kinase 2 (JAK2) gene." (PMID 38566064, 2024). "The elevated platelet count, in conjunction with imaging findings and the genetic confirmation of the JAK2 V617F mutation, pointed towards an underlying essential thrombocythemia as the likely etiology." (PMID 39877786, 2024). "The occurrence of somatic JAK2 mutations has been very thoroughly described in MPNs, including PV, Essential Thrombocythemia (ET), and primary myelofibrosis." (PMID 37239426, 2023). "JAK2 mutations, such as V617F, have been found recurrently in MPNs, including essential thrombocytosis." (PMID 36874138, 2023). "This somatic JAK2 mutation V617F is known to have been reported in most patients with polycythemia vera (PV), as well as in approximately one-third of patients with essential thrombocythemia and or idiopathic myelofibrosis." (PMID 37508780, 2023). "Molecular diagnosis of MPN occurs from the presence of mutant JAK2-V617F and associated diseases include essential thrombocythemia (ET) and myelofibrosis (MF) of which NPM1-mutations have been found on a rare occasion." (PMID 36834572, 2023). "Essential thrombocythemia is a blood cancer characterized by an overproduction of platelets mediated via a pathway in megakaryocytes involving variants of JAK2, MPL, and CALR." (PMID 36979444, 2023). "In patients with essential thrombocythemia or primary myelofibrosis, mutations in the Janus kinase 2 (JAK2) gene, mutations in exon 9 of the calreticulin gene, and activating mutations in the thrombopoietin receptor gene (MPL) are detected." (PMID 35216363, 2022). "This patient's history of JAK2 essential thrombocytosis predisposes her to thrombosis formation, which is a significant cause of morbidity and mortality in this patient population and is reported to occur in 20% of patients." (PMID 35891817, 2022). "It should also be noted that, while they are described in PV patients, most of the atypical JAK2 mutations within exon 14 have been associated with the profile of essential thrombocythemia." (PMID 35456443, 2022). "A mutation in the JAK2 kinase domain is found in approximately 95% of patients with polycythemia vera (PV) and 50% of patients with essential thrombocytosis (ET) and myelofibrosis (MF), which causes pathogenesis at the molecular level." (PMID 36699049, 2022).